H3C12 (H3 clustered histone 12)
Description:
Core component of nucleosome. Nucleosomes wrap and compact DNA into chromatin, limiting DNA accessibility to the cellular machineries which require DNA as a template. Histones thereby play a central role in transcription regulation, DNA repair, DNA replication and chromosomal stability. DNA accessibility is regulated via a complex set of post-translational modifications of histones, also called histone code, and nucleosome remodeling.
Synonyms: H3FJ; HIST1H3J; H3/j
Tractability: Small molecule: a structure with a bound ligand is known. Antibody: its Gene Ontology location is reachable by antibodies, with high confidence. PROTAC: UniProt records ubiquitination sites on it; ubiquitination databases record sites on it.
Gene: Protein-coding gene on chromosome 6 (27,890,315 to 27,893,106, reverse strand). Ensembl gene ENSG00000197153.
Subcellular location: Nucleus; Chromosome
Subcellular location (Human Protein Atlas): Nucleoplasm
Pathways (Reactome):
Gene expression (Transcription): B-WICH complex positively regulates rRNA expression; DNA methylation; ERCC6 (CSB) and EHMT2 (G9a) positively regulate rRNA expression; MLL4 and MLL3 complexes regulate expression of PPARG target genes in adipogenesis and hepatic steatosis; NoRC negatively regulates rRNA expression; PRC2 methylates histones and DNA; RNA Polymerase I Promoter Escape; RNA Polymerase I Promoter Opening; RUNX1 regulates genes involved in megakaryocyte differentiation and platelet function; RUNX1 regulates transcription of genes involved in differentiation of HSCs; Regulation of endogenous retroelements by KRAB-ZFP proteins; Regulation of endogenous retroelements by Piwi-interacting RNAs (piRNAs); Regulation of endogenous retroelements by the Human Silencing Hub (HUSH) complex; SIRT1 negatively regulates rRNA expression; Transcriptional regulation by small RNAs
Chromatin organization: CHD1 and CHD2 subfamily; CHD6, CHD7, CHD8, CHD9 subfamily; ChAHP complex assembly; Chromatin modifying enzymes; HATs acetylate histones; HDACs deacetylate histones; HDMs demethylate histones; Interaction of NuRD complexes with transcription factors; NuRD complex assembly; PKMTs methylate histone lysines; RMTs methylate histone arginines
Disease: Defective pyroptosis; Dengue Virus-Host Interactions; HCMV Early Events; HCMV Late Events
Signal Transduction: Activated PKN1 stimulates transcription of AR (androgen receptor) regulated genes KLK2 and KLK3; Estrogen-dependent gene expression; Formation of the beta-catenin:TCF transactivating complex; Pre-NOTCH Transcription and Translation
Developmental Biology: Activation of anterior HOX genes in hindbrain development during early embryogenesis; Chromatin modifications during the maternal to zygotic transition (MZT); Transcriptional regulation of granulopoiesis
Immune System: FXIIa activates plasma kallikrein-kinin system; Interleukin-7 signaling; Regulation of PD-L1(CD274) transcription
and 8 more pathways
Gene Ontology:
Molecular function: cadherin binding; protein binding; structural constituent of chromatin; nucleosomal DNA binding; DNA binding; protein heterodimerization activity
Biological process: epigenetic regulation of gene expression; nucleosome assembly; chromatin organization; heterochromatin formation; telomere organization
Cellular component: chromatin; extracellular exosome; membrane; nucleoplasm; nucleosome; nucleus; protein-containing complex; extracellular region; chromosome
Genetic constraint (gnomAD): Loss-of-function variants: 7 observed, 7.85 expected, observed/expected ratio (o/e) 0.89, 90% interval 0.5 to 1.62. That is too few expected variants to judge how well the gene tolerates losing a copy. Missense variants: 167 observed, 203.68 expected, observed/expected ratio (o/e) 0.82, 90% interval 0.72 to 0.93. Synonymous variants: 100 observed, 79.59 expected, observed/expected ratio (o/e) 1.26, 90% interval 1.07 to 1.48.
Homologues: Orthologues: rat Hist1h3b (100% identical), Drosophila melanogaster His3:CG33812 (99% identical), zebrafish si:ch1073-153i20.2 (99% identical), zebrafish si:ch211-113a14.20 (99% identical), zebrafish si:ch211-113a14.23 (99% identical), zebrafish si:ch211-113a14.27 (99% identical), zebrafish zgc:173552 (99% identical), Caenorhabditis elegans his-17 (97% identical), Caenorhabditis elegans his-2 (97% identical), Caenorhabditis elegans his-32 (97% identical), Caenorhabditis elegans his-40 (97% identical), Caenorhabditis elegans his-42 (97% identical), and 6 more. Paralogues in human: H3C1 (100% identical), H3C10 (100% identical), H3C11 (100% identical), H3C2 (100% identical), H3C3 (100% identical), H3C4 (100% identical), H3C6 (100% identical), H3C7 (100% identical), H3C8 (100% identical), H3C13 (99% identical), H3C14 (99% identical), H3C15 (99% identical), and 8 more.
Diseases named in the same sentence as H3C12 in open-access papers:
H3C12 is named in the same sentence as 3 diseases in open-access papers, as found by Europe PMC text mining. Sharing a sentence is not in itself a finding about the gene and the disease. The quoted sentences say what the papers report.
cancer (2 papers, 2021 to 2025). A tumor composed of atypical neoplastic, often pleomorphic cells that invade other tissues. "The protein network of unique cancer cell genes in the “cancer cells_vs_all-PDAC” group exhibited top 10 hub genes, including H4C6 (HIST1H4A or HIST1H4C), MYC, H3C12 (HIST1H3A or HIST1H3D), DDX21, USP7, RFC4, APEX1, CDK9, H2BC9 (HIST1H2BH), and NOP2." (PMID 40906153, 2025).
H3C12 also shares sentences with these, for which no sentence is quoted: gastric cancer (1 paper); systemic lupus erythematosus (1).